ZFP1 (ZFP1 zinc finger protein)
Description:
May be involved in transcriptional regulation.
Synonyms: ZNF475; PITA; FLJ34243
Tractability: PROTAC: UniProt records ubiquitination sites on it; ubiquitination databases record sites on it.
Gene: Protein-coding gene on chromosome 16 (75,148,494 to 75,172,236, forward strand). Ensembl gene ENSG00000184517.
Subcellular location: Nucleus
Subcellular location (Human Protein Atlas): Nucleoplasm
Pathways (Reactome):
Gene expression (Transcription): Generic Transcription Pathway
Gene Ontology:
Molecular function: protein binding; sequence-specific double-stranded DNA binding; DNA-binding transcription factor activity, RNA polymerase II-specific; RNA polymerase II cis-regulatory region sequence-specific DNA binding
Biological process: regulation of transcription by RNA polymerase II; regulation of DNA-templated transcription
Cellular component: nucleus
Genetic constraint (gnomAD): Loss-of-function variants: 32 observed, 40.51 expected, observed/expected ratio (o/e) 0.79, 90% interval 0.6 to 1.06. The synonymous counts are far from expectation, so gnomAD's model fits this gene poorly and the ratio says little. Missense variants: 616 observed, 505.14 expected, observed/expected ratio (o/e) 1.22, 90% interval 1.14 to 1.3. Synonymous variants: 245 observed, 178.24 expected, observed/expected ratio (o/e) 1.37, 90% interval 1.24 to 1.53.
Homologues: Orthologues: chimpanzee ZFP1 (99% identical), macaque ZFP1 (98% identical), dog ZFP1 (93% identical), pig ZFP1 (92% identical), guinea pig ZFP1 (88% identical), rabbit ZFP1 (88% identical), mouse Zfp1 (86% identical), rat Zfp1 (85% identical). Paralogues in human: ZNF33B (53% identical), ZNF658 (52% identical), ZNF300 (51% identical), ZNF717 (50% identical), ZNF585B (50% identical), ZNF182 (49% identical), ZNF334 (49% identical), ZNF41 (49% identical), ZNF484 (49% identical), ZNF568 (49% identical), ZNF546 (49% identical), ZNF250 (48% identical), and 164 more.
Diseases named in the same sentence as ZFP1 in open-access papers:
ZFP1 is named in the same sentence as 18 diseases in open-access papers, as found by Europe PMC text mining. Sharing a sentence is not in itself a finding about the gene and the disease. The quoted sentences say what the papers report.
acute myeloid leukemia (1 paper, 2013). Acute myeloid leukemia (AML) is a group of neoplasms arising from precursor cells committed to the myeloid cell-line differentiation. "The human homolog of zfp-1 is called AF10 and is involved in pediatric acute myeloid leukemia (AML) making zfp-1 an interesting gene to explore." (PMID 24066155, 2013).
Fanconi anemia (1 paper, 2008). Fanconi anemia (FA) is a hereditary DNA repair disorder characterized by progressive pancytopenia with bone marrow failure, variable congenital malformations and predisposition to develop hematological or solid tumors. "The remaining third includes four genes conserved in nematodes, fly, mouse, and human (zfp-1, R11F4.1, apl-1 and fcd-2) and whose human homologs are linked to disorders (AF10/MLLT10: leukemia, Glycerol kinase: hyperglycerolemia, APP: Alzheimer's, and FANCD2: Fanconi anemia)." (PMID 18752680, 2008).
infection (7 papers, 2011 to 2025). The state of being infected such as from the introduction of a foreign agent such as serum, vaccine, antigenic substance or organism. "Upon exposure to PA14 under the standard infection assay conditions, we observed that the zfp-1(ok554) mutants were significantly more susceptible to P. aeruginosa infection- mediated killing." (PMID 21980302, 2011). "In the infection assays, the zfp1 lesion diameters in the detached leaves and rhizomes were significantly decreased compared to ZFP1 and zfp1 tZFP1." (PMID 38992190, 2024). "We confirmed that age-1(hx546) was more resistant to the infection and tested age-1; zfp-1 double mutants." (PMID 21980302, 2011). "Future studies exploring the function of zfp-1–1 in the context of host infection could provide important insights into the role for tegmental renewal in parasite survival in vivo." (PMID 29557781, 2018). "Stress response assays showed that deletion or overexpression of Zfp1 increased susceptibility to sodium dodecyl sulfate (SDS), but not Congo red, demonstrating that Zfp1 may govern cell membrane integrity, which may be one of the reasons the virulence declined in a murine systemic-infection model." (PMID 32085473, 2020).
ZFP1 also shares sentences with these, for which no sentence is quoted: adenocarcinoma (1 paper); adenosquamous carcinoma (1); Alzheimer disease (1); cancer (1); colon cancer (1); colorectal cancer (1); colorectal tumor (1); Granuloma (1); hyperglycerolemia (1); leukemia (1); pancreatic cancer (1); rectal cancer (1); rectal tumor (1); squamous cell carcinoma (1); tumor (1).